BSDC1 (BSD domain containing 1)
Synonyms: FLJ10276; RP4-811H24.7
Tractability: PROTAC: ubiquitination databases record sites on it; its protein half-life has been measured.
Gene: Protein-coding gene on chromosome 1 (32,364,633 to 32,394,731, reverse strand). Ensembl gene ENSG00000160058.
Subcellular location (Human Protein Atlas): Golgi apparatus; Plasma membrane
Gene Ontology:
Molecular function: protein binding
Cellular component: Golgi apparatus; cytoplasm
Genetic constraint (gnomAD): Loss-of-function variants: 27 observed, 48.78 expected, observed/expected ratio (o/e) 0.55, 90% interval 0.41 to 0.76. The upper end of that interval is the gene's LOEUF score, 0.76, which puts it in group 3 of 6, group 1 being the genes least tolerant of losing a copy. Missense variants: 473 observed, 527.16 expected, observed/expected ratio (o/e) 0.9, 90% interval 0.83 to 0.97. Synonymous variants: 210 observed, 205.54 expected, observed/expected ratio (o/e) 1.02, 90% interval 0.91 to 1.15.
Homologues: Orthologues: chimpanzee BSDC1 (99% identical), macaque BSDC1 (97% identical), mouse Bsdc1 (92% identical), dog BSDC1 (91% identical), guinea pig BSDC1 (90% identical), pig BSDC1 (90% identical), rabbit BSDC1 (90% identical), rat Bsdc1 (90% identical), tropical clawed frog bsdc1 (63% identical), zebrafish bsdc1 (61% identical), Caenorhabditis elegans Y97E10AR.6 (23% identical). Paralogues in human: SYAP1 (15% identical).
Diseases named in the same sentence as BSDC1 in open-access papers:
BSDC1 is named in the same sentence as 6 diseases in open-access papers, as found by Europe PMC text mining. Sharing a sentence is not in itself a finding about the gene and the disease. The quoted sentences say what the papers report.
breast carcinoma (1 paper, 2020). "Further experimentation should explicitly assess the biological function of BSDC1 in order to validate its role as an oncogene and examine its potential as a molecular target in breast cancer." (PMID 33087122, 2020). "Similarly, little is known about the involvement of BSDC1 in breast cancer." (PMID 33087122, 2020).
breast tumors (1 paper, 2020). "We found that BSDC1 was overexpressed in breast tumors, suggesting that BSDC1 may be an important driver of carcinogenesis." (PMID 33087122, 2020).
glioblastoma (1 paper, 2020). The most malignant astrocytic tumor (WHO grade IV). "The specific function of BSDC1 remains unknown; however, copy number variations in BSDC1 have been observed in ER-negative breast tumors, and sequence mutations in the gene have been associated with glioblastoma tumorigenesis." (PMID 33087122, 2020).
uveal melanoma (1 paper, 2023). A melanoma derived from melanocytes of the uveal tract. "Studies of target genes and pathways in uveal melanoma (UM) have shown that target genes, such as BSDC1, have been extracted by miRNA-mRNA correlations." (PMID 36930617, 2023).
tumor (2 papers, 2020 to 2023). "Otherwise, BSDC1 is a novel gene that can detect tumor subtypes." (PMID 36930617, 2023). "Not only did we confirm known oncogenes, but we also propose novel tumorigenic genes, such as BSDC1 and U2AF1, that could distinguish between tumor subtypes." (PMID 33087122, 2020).
cancer (1 paper, 2020). A tumor composed of atypical neoplastic, often pleomorphic cells that invade other tissues. "When examining the top 100 gene pairs, BSDC1, C3orf14, CDR2L, LRRC42, MEOX2, NRG2, and PLEKHA6, and SCARF1 were consistently identified by feature selection methods to be associated with cancer status." (PMID 33087122, 2020). "Interestingly, C3orf14, CDR2L, LRRC42, MEOX2, NRG2, and SCARF1 are known carcinogenic genes, while BSDC1 and PLEKHA6 have not been described in previous cancer literature." (PMID 33087122, 2020).